ABI1 (abl interactor 1)
Description:
May act in negative regulation of cell growth and transformation by interacting with nonreceptor tyrosine kinases ABL1 and/or ABL2. May play a role in regulation of EGF-induced Erk pathway activation. Involved in cytoskeletal reorganization and EGFR signaling. Together with EPS8 participates in transduction of signals from Ras to Rac. In vitro, a trimeric complex of ABI1, EPS8 and SOS1 exhibits Rac specific guanine nucleotide exchange factor (GEF) activity and ABI1 seems to act as an adapter in the complex. Regulates ABL1/c-Abl-mediated phosphorylation of ENAH. Recruits WASF1 to lamellipodia and there seems to regulate WASF1 protein level. In brain, seems to regulate the dendritic outgrowth and branching as well as to determine the shape and number of synaptic contacts of developing neurons.
Synonyms: Abi-1; AblBP4; Nap1BP; SSH3BP1; E3B1; SSH3BP
Tractability: Antibody: the Human Protein Atlas places it where antibodies can reach. PROTAC: ubiquitination databases record sites on it; its protein half-life has been measured.
Gene: Protein-coding gene on chromosome 10 (26,745,942 to 26,861,094, reverse strand). Ensembl gene ENSG00000136754.
Subcellular location: Cytoplasm; Nucleus; Cell projection, lamellipodium; Cell projection, filopodium; Cell projection, growth cone; Postsynaptic density; Cytoplasm, cytoskeleton
Subcellular location (Human Protein Atlas): Cell Junctions; Plasma membrane
Pathways (Reactome):
Signal Transduction: RAC1 GTPase cycle; RAC2 GTPase cycle; RAC3 GTPase cycle; RHO GTPases Activate WASPs and WAVEs; VEGFA-VEGFR2 Pathway
Disease: FCGR3A-mediated phagocytosis
Immune System: Regulation of actin dynamics for phagocytic cup formation
Gene Ontology:
Molecular function: cadherin binding; protein binding; SH3 domain binding; signaling adaptor activity; cytoskeletal protein binding; protein tyrosine kinase activator activity
Biological process: positive regulation of protein tyrosine kinase activity; actin polymerization or depolymerization; cell surface receptor protein tyrosine kinase signaling pathway; negative regulation of cell population proliferation; neuron migration
Cellular component: extracellular exosome; filopodium tip; lamellipodium; SCAR complex; actin-based cell projection; cytosol; endoplasmic reticulum; cell leading edge; cytoplasm; cytoskeleton; filopodium; growth cone; neuron projection; nucleus; postsynaptic density
Genetic constraint (gnomAD): Loss-of-function variants: 13 observed, 50.38 expected, observed/expected ratio (o/e) 0.26, 90% interval 0.17 to 0.41. The upper end of that interval is the gene's LOEUF score, 0.41, which puts it in group 1 of 6, group 1 being the genes least tolerant of losing a copy. Missense variants: 430 observed, 613.01 expected, observed/expected ratio (o/e) 0.7, 90% interval 0.65 to 0.76. Synonymous variants: 193 observed, 214.92 expected, observed/expected ratio (o/e) 0.9, 90% interval 0.8 to 1.01.
Cancer hallmarks: invasion and metastasis (promotes); proliferative signalling (promotes); suppression of growth (promotes); invasion and metastasis (suppresses)
Homologues: Orthologues: chimpanzee ABI1 (100% identical), macaque ABI1 (100% identical), pig ABI1 (100% identical), rabbit ABI1 (99% identical), rat Abi1 (99% identical), dog ABI1 (98% identical), mouse Abi1 (98% identical), guinea pig ABI1 (97% identical), tropical clawed frog abi1 (92% identical), zebrafish abi1a (85% identical), zebrafish abi1b (84% identical). Paralogues in human: ABI2 (75% identical), ABI3 (36% identical).
Diseases named in the same sentence as ABI1 in open-access papers:
ABI1 is named in the same sentence as 54 diseases in open-access papers, as found by Europe PMC text mining. Sharing a sentence is not in itself a finding about the gene and the disease. The quoted sentences say what the papers report.
breast carcinoma (18 papers, 2010 to 2025). "An analysis of 1,903 breast cancer patients found that ABI1 overexpression is associated with more aggressive cancer." (PMID 39354505, 2024). "Another potential co-target is ABI1, which acts as an oncogene in breast cancer cells and is associated with aggressive phenotypes." (PMID 38067367, 2023). "ABI1 is associated with poor survival and an aggressive breast cancer phenotype, although its role in tumorigenesis, metastasis, and the disease outcome remains to be elucidated." (PMID 34967509, 2022). "Our findings indicate the significant predictive value of the ABI1‐based 7‐gene prognostic signature derived from primary tumors in the metastatic risk of breast cancer patients." (PMID 34967509, 2022). "The deficiency of ABI1 has been shown to reduce cell migration and invasiveness of aggressive breast cancer cells and is associated with activity in pathways such as PI3 kinase/AKT and SRC." (PMID 34967509, 2022). "To determine the impact of Abi1 disruption on mammary tumor initiation and progression, we used our Abi1 KO mouse model to study the impact of Abi1 loss on tumor progression and characteristics in the PyMT‐driven breast cancer." (PMID 34967509, 2022). "Firstly, we focused on the identification of the role of ABI1 expression in breast cancer survival associated with cancer progression/recurrence (defined DFS time) and metastatic process (DMFS time)." (PMID 34967509, 2022). "We demonstrate, for the first time, that lung metastasis is associated with an Abi1 gene dose and specific gene expression aberrations in primary breast cancer tumors." (PMID 34967509, 2022). "As there is a concomitant loss of WAVE2 upon Abi1 KO but sustained tumor growth in PyMT mammary tumors, it is possible that other factors contribute to ARP2/3‐mediated actin polymerization." (PMID 34967509, 2022). "shRNA-mediated knockdown of Abi1 in PTEN-deficient breast cancer cells reverses the EMT and reduces CSCs." (PMID 32728066, 2020). "If Abi1 elevation in PTEN-deficient breast cancer causes the EMT and enriches CSC activity, depletion of Abi1 should suppress these processes." (PMID 32728066, 2020). "In summary, we demonstrated that Abi1 is significantly upregulated in PTEN-deficient breast cancer cells." (PMID 32728066, 2020). "It was shown that Abi1 is significantly upregulated in PTEN-deficient breast cancer cells." (PMID 35954450, 2022). "Moreover, ABI1 overexpression is associated with highly aggressive (grade 3) basal‐like and claudin‐low breast cancer subtypes." (PMID 34967509, 2022). "Thus, we aimed to study the impact of Abi1 loss on mammary tumor initiation and progression using the polyoma middle T (PyMT) breast cancer mouse model." (PMID 34967509, 2022). "Importantly, the prognostic association ‘higher risk – the higher the expression’ of ABI1 was statistically significant and reproducible over breast cancer cohorts." (PMID 34967509, 2022). "High levels of ABI1 have been associated with the risks of metastasis of primary tumors and breast cancer mortality, as well as associated with the metastatic phenotype of human breast cancer cell lines in vitro." (PMID 34967509, 2022). "Additionally, dysregulation of ABI1 was confirmed associated with the prognosis of gastric cancer, epithelial ovarian cancer, and breast cancer." (PMID 34195183, 2021). "Likewise, ABI1, an adaptor protein involved in cell migration, along with its downstream effector phospho-Akt (p-Akt), has been implicated in the spread of breast cancer; is positively correlated with reduced H3K27me3K36me3 (p-val <7.02e-05) when inhibited by CDK inhibitor flavopiridol." (PMID 32412527, 2020). "The ABI1 gene was shown to have played a role in tumor invasion and metastasis in breast cancer in a study conducted in 2021." (PMID 38954213, 2025).
breast carcinoma (continued). "As breast cancer prognosis is highly dependent on metastatic potential, the role of ABI1 in promoting cell migration offers mechanistic insight to both better understanding pathobiology and providing therapeutic direction." (PMID 39354505, 2024). "ABI1 is also identified as a prognostic marker for breast cancer metastasis and shows a gene dose-response in mice positively correlated with number of pulmonary metastases." (PMID 39354505, 2024). "To model the role of Abi1 in breast cancer tumor progression and metastasis, we conditionally depleted Abi1 gene expression in the mammary epithelium of PyMT breast cancer mice using the mammary‐specific Cre recombinase mouse." (PMID 34967509, 2022). "Here, for the first time, we demonstrate the metastasis driver role of ABI1 in breast cancer tumor progression using the PyMT mouse model and clinical data from breast cancer patients." (PMID 34967509, 2022). "Genetic disruption of Abi1 in primary breast cancer tumors of PyMT mice led to significant reduction of the number and size of lung metastases in a gene dose‐dependent manner." (PMID 34967509, 2022). "Gene expression variability upon Abi1 depletion in primary PyMT breast cancer tumors defined by RNA‐seq." (PMID 34967509, 2022). "Previously, immunohistochemical studies of over 900 human breast tumor samples showed that ABI1 overexpression is positively correlated with poor survival and a shorter relapse time in human breast cancer patients." (PMID 34967509, 2022). "Here, we define the ABI1‐based seven‐gene prognostic signature that predicts survival of metastatic breast cancer patients; ABI1 is an essential component of the signature." (PMID 34967509, 2022). "Several in vitro studies have shown the impact of ABI1 in driving breast cancer cell motility, division, and invasiveness; however, its exact role during in vivo tumor initiation, progression, and metastasis remains to be elucidated." (PMID 34967509, 2022). "This is the first genetic study examining the role of Abi1 in vivo using the mouse model of aggressive breast cancer." (PMID 34967509, 2022). "By comparing the effects of one‐ and two‐allele inactivation of the Abi1 gene, we were able to determine that ABI1 expression levels play an important pro‐oncogenic role in breast cancer tumor progression and metastatic disease." (PMID 34967509, 2022). "Our survival prediction analyses establish the significance of ABI1 gene expression as a pro‐oncogenic factor of primary tumor formation and metastasis in breast cancer patients." (PMID 34967509, 2022). "We found essential differences for both characteristics in the breast cancer metastases in the ABI1 gene dosage‐dependent manner." (PMID 34967509, 2022). "Our data adhere to previously published findings regarding the impact of ABI1 protein in driving aggressive mammary oncogenesis in mouse xenograft models of breast cancer." (PMID 34967509, 2022). "In cultured breast cancer cells, Abi1 formed a complex with IRS53 to activate Rac1, which drives lamellipodial formation." (PMID 32728066, 2020). "Abl interactor 1 (Abi1) is a critical regulator of actin polymerization/depolymerization, involving in the abnormal development of cytoskeletal functions of breast cancer cells." (PMID 32410828, 2020). "On the other hand, depletion of Abi1 in breast cancer cells suppresses the EMT and inhibits CSC activity, mimicking the effect of PTEN reconstitution." (PMID 32728066, 2020). "In breast cancer, high levels of Abi1 expression correlates with early recurrence and poor prognosis." (PMID 32728066, 2020). "Combined with the overexpression studies, these results suggest that elevation of Abi1, induced by PTEN loss, contributes to the EMT and increased CSC activity in breast cancer." (PMID 32728066, 2020).
breast carcinoma (continued). "Stable transfection of BT549 cells with PTEN decreased Abi1 and its phosphorylation at Y213 and S216, which confirmed that PTEN also dephosphorylates and negatively regulates the Abi1 protein in breast cancer cells." (PMID 32728066, 2020). "In concordance with this finding, less invasive breast cancer cell lines express lower levels of Abi1, whereas highly invasive breast cancer cell lines express high levels of Abi181." (PMID 32728066, 2020). "Abi1 serves as a substrate for PTEN and is significantly upregulated in PTEN-deficient breast cancer cells." (PMID 32728066, 2020). "Taken together, these results suggest that PTEN dephosphorylates and downregulates Abi1 in breast cancer cells." (PMID 32728066, 2020). "In invading breast cancer cells, Abi1 is required for invadopodia formation and matrix-metalloproteinase 9 secretion." (PMID 24913355, 2014). "Overexpression of ABI-1 correlates well with migratory and invasion potential in breast cancer cell lines, while suppression of this protein led to the complete loss of migratory ability in once highly invasive cell lines." (PMID 20406439, 2010). "ABI1 also promotes breast cancer progression and metastasis." (PMID 39354505, 2024). "ABI1 is more abundant in highly invasive breast cancer cell lines, and downregulation of ABI1 by RNA interference results in decreased lamellipodia formation, decreased adhesion, decreased proliferation, and decreased migration and invasion linked to defective PI3K/AKT and WRC signaling." (PMID 39354505, 2024). "ABI1 also localizes to invadopodia in MDA-MB-231 breast cancer cell lines, and ABI1 knockdown impairs invadopodia formation, inhibits tumor cell proliferation and migration, decreases SRC activation, and downregulates matrix metalloproteinase 9 (MMP9) expression." (PMID 39354505, 2024). "In conclusion, ABI1 is a prognostic metastatic biomarker in breast cancer." (PMID 34967509, 2022). "Collectively, both our analyses utilizing both human breast cancer gene expression data and genetically engineered Abi1 knockout breast cancer mouse models support the critical role of ABI1 and ABI1‐based gene prognostic signature as novel biomarkers of breast cancer metastases." (PMID 34967509, 2022). "The important role of ABI1 in breast cancer has been established in clinical samples." (PMID 34967509, 2022). "PTEN dephosphorylates and downregulates Abi1 in breast cancer cells." (PMID 32728066, 2020). "Elevation of Abi1 after PTEN loss may be responsible for the EMT and increased CSC activity in breast cancer." (PMID 32728066, 2020). "This is consistent with the described role of Abi1 in breast cancer cell invadopodia formation and might explain the inhibition of colorectal cancer cell migration and invasion through STI571 that has been previously shown." (PMID 24913355, 2014). "Furthermore, Abi1 has been shown to be a positive regulator of breast cancer cell proliferation, migration and invasion." (PMID 22808230, 2012). "Importantly, the ABI1‐based prognostic signature could serve as a predictive tool for a metastatic event of breast cancer patients." (PMID 34967509, 2022). "Interestingly, comparative analysis of the basal‐like vs. luminal breast cancer cell types markers in ABI1 KO mice showed that the genes of basal‐like cells (Krt14, Vim) are responded to Abi1 depletion, however luminal cell type genes markers (Krt8, Krt18, Sox9, Estr1) do not." (PMID 34967509, 2022). "Thus, ABI1 expression shows strong positive correlates with histologic grading, negative correlation with ER status, and represents correctly the known ranked‐order of breast cancer subtypes according to their genetic grading classification." (PMID 34967509, 2022). "Notably, all studies to date examined the role of ABI1 in breast cancer using cancer cell lines." (PMID 34967509, 2022).
breast carcinoma (continued). "While the studies of breast cancer and colorectal carcinoma cells support a role of Abi1 in breast cancer and colorectal cancer development in vitro and in vivo, other studies suggest that Abi1 may function as a tumor suppressor in prostate cancer and gastric carcinoma development." (PMID 32276588, 2020). "While some of the top candidates have been previously reported to play a role in cancer (FLNB, MAP3K7, NFYA, and ESYT2) others were identified to be breast cancer-relevant for the first time (NEDD4L, MARK2, ABI1)." (PMID 38664594, 2024). "Another study found that restoring PTEN in breast cancer prevented EMT and stemness through the downregulation of Abelson interactor 1 (Abi1)." (PMID 37190236, 2023). "The protein phosphatase activity of PTEN is required for the dephosphorylation and degradation of Abi1, which otherwise promotes EMT in breast cancer." (PMID 35954450, 2022). "Our bioinformatics analyses revealed the significant role of human ABI1 and a subset of the WAVE complex genes in the context of breast cancer progression and metastatic process." (PMID 34967509, 2022). "To elucidate the significance of the ABI1 in the pathobiology of human breast cancer, we carried out a retrospective analysis of METABRIC data of 1904 breast cancer patients." (PMID 34967509, 2022). "Moreover, overall primary mammary tumor histopathology was not affected upon ABI1 loss." (PMID 34967509, 2022). "Pten loss has also been shown to promote EMT, and recent work suggests that Pten restoration in breast cancer models inhibits EMT and stemness CSCs activity via Abi1 (Abelson interactor 1) downregulation." (PMID 34946849, 2021). "Another study showed that ABI1 has an inverse function, and its upregulation induced the EMT process and increased stem cell activity in breast cancer." (PMID 34944712, 2021). "To date, in vivo study on the role of ABI1 in tumor metastasis has been mainly related to the study of leukemia, breast cancer, and liver cancer, but there are no related reports on CRC." (PMID 34031495, 2021).